PGRMC1 (progesterone receptor membrane component 1)
Diseases named in the same sentence as PGRMC1 in open-access papers (continued):
Sharing a sentence is not in itself a finding about the gene and the disease.
brain injury (1 paper, 2024). Acute and chronic (see also brain INJURIES, CHRONIC) injuries to the brain, including the cerebral hemispheres, CEREBELLUM, and brain STEM. "In neurology, PGRMC1 regulates the proliferation of neural progenitor cells, modulates synaptic remodeling, protects against hypoxic–ischemic brain injury, and protects against spinal cord-associated diseases or traumatic brain injuries." (PMID 38397828, 2024).
brain tumours (1 paper, 2023). "Progesterone Receptor Membrane Component 1 (PGRMC1) is a tumour-promoting factor in several types of cancer but its role in brain tumours is poorly characterized thus far." (PMID 37887342, 2023).
cardiac hypertrophy (1 paper, 2021). "HFD Pgrmc1 KO hearts was not linked with cardiac hypertrophy according to similar HW/BW and HW/tibial length to those of HFD WT mice." (PMID 33888830, 2021). "Based on these results, we concluded that the metabolic phenotype of Pgrmc1 KO mice leads to cardiac lipotoxicity under HFD conditions, but does not trigger cardiac hypertrophy." (PMID 33888830, 2021).
cardiomyopathy (1 paper, 2023). A disease of the heart muscle or myocardium proper. "Using public clinical datasets, we collected data to investigate the relationship between PGRMC1 expression and cardiomyopathy." (PMID 36899888, 2023).
cataract (1 paper, 2021). Partial or complete opacity of the crystalline lens of one or both eyes that decreases visual acuity and eventually results in blindness. "The PGRMC1 truncating 127 kb deletion is a novel cause of the X-linked isolated paediatric cataracts in this Australian family." (PMID 33867527, 2021).
Cerebral ischemia (1 paper, 2020). Restriction of arterial blood supply to the brain associated with insufficient oxygenation to support the metabolic requirements of the tissue. "Interestingly, a recent study in mice showed a decrease in PGRMC1 protein level in the cortical penumbra at day 7 following cerebral ischemia." (PMID 32722286, 2020).
cervical squamous cell carcinoma (1 paper, 2025). A squamous cell carcinoma arising from the cervical epithelium. "At the clinical level, we collected cervical biopsy specimens from HPV-positive patients and verified the expression patterns of PGRMC1 and VIM using immunohistochemical staining in cervical squamous cell carcinoma (CSCC) tissues." (PMID 41153737, 2025).
cervical squamous intraepithelial lesion (1 paper, 2025). "We found that PGRMC1 binds to and regulates VIM phosphorylation to promote cervical squamous intraepithelial lesion progression." (PMID 41153737, 2025).
cervical tumors (1 paper, 2025). "PGRMC1 is implicated in hormone sensitivity and cholesterol synthesis regulation via the Akt signaling pathway and has been extensively studied in endometrial and cervical tumors." (PMID 40949879, 2025).
cervicitis (1 paper, 2025). An acute or chronic inflammatory process that affects the cervix. "The results indicated a gradual intensification of PGRMC1 staining from the Cervicitis group to the LSIL group, then to the HSIL group, with the CSCC group also displaying strong staining." (PMID 41153737, 2025). "Both the positive area and positive rate were utilized to assess the protein expression of PGRMC1 in the tissues of Cervicitis, LSIL, HSIL, and CSCC." (PMID 41153737, 2025). "Furthermore, compared to the Cervicitis group, the high positive rate of PGRMC1 protein in HSIL tissues was significantly elevated." (PMID 41153737, 2025). "The findings revealed a progressive increase in the positive area of PGRMC1 staining from the Cervicitis group to the CSCC group, suggesting that PGRMC1-positive cells gradually dominated the cervical tissue during the transition from CIN to CSCC." (PMID 41153737, 2025).
clear cell carcinomas (1 paper, 2015). "In ovarian tissues, PGRMC1 staining was not significantly different in normal ovarian tissue compared to tumor adjacent tissue, clear cell carcinomas or mucinous papillary adenocarcinomas." (PMID 27867772, 2015).
colorectal cancer (1 paper, 2023). A primary or metastatic malignant neoplasm that affects the colon or rectum. "Targeting the PGRMC1/NENF complex may open-up new therapeutic possibilities for patients with colorectal cancer." (PMID 37894441, 2023). "PGRMC1 inhibition abolishes the effect of P4, suggesting that P4 in advanced colorectal cancer may act primarily through PGRMC1." (PMID 37894441, 2023). "Targeting the PGRMC1/NENF complex may open-up new therapeutic possibilities for patients with advanced colorectal cancer." (PMID 37894441, 2023). "Therefore, future studies aimed at developing treatment strategies for colorectal cancer could consider simultaneous PGRMC1 inhibition along with a blockage of NENF production and secretion." (PMID 37894441, 2023). "Our data may provide the novel insights into the action of P4, PGRMC1, and NENF in colorectal cancer." (PMID 37894441, 2023). "Taken together, our data provided novel insights into the actions of P4, PGRMC1, and NENF in colorectal cancer, emphasizing new potential actions that may regulate CRC biology." (PMID 37894441, 2023).
cyst (1 paper, 2016). A sac-like closed membranous structure that may be empty or contain fluid or amorphous material. "In addition, loss of function of PGRMC1 abolished P4-induced inhibition of cyst breakdown and follicle formation." (PMID 27848973, 2016).
diabetic cardiomyopathy (1 paper, 2023). Diabetic cardiomyopathy is a disorder of the heart muscle in people with diabetes. "Notably, Pgrmc1 has also been associated with diabetic cardiomyopathy, as it reduces lipid-mediated toxicity and delays cardiac injury." (PMID 36899888, 2023).
dilated cardiomyopathy (1 paper, 2023). Cardiomyopathy which is characterized by dilation and contractile dysfunction of the left and right ventricles. "In GSE36961, the hearts of patients with dilated cardiomyopathy with left ventricular systolic dysfunction showed decreased PGRMC1 expression levels compared to those of normal individuals." (PMID 36899888, 2023). "In GSE29819, both ventricles from patients with dilated cardiomyopathy showed lower PGRMC1 expression levels than those from non-failing donor hearts." (PMID 36899888, 2023).
endometrial tumors (1 paper, 2021). "Taken together, these xenograft studies demonstrate that the presence of PGRMC1 differentially affects the ability of various chemotherapeutic agents to destroy ovarian and endometrial tumors." (PMID 34885064, 2021). "Taken together, these xenograft studies clearly demonstrate that PGRMC1 plays important roles in growth and chemosensitivity of both ovarian and endometrial tumors." (PMID 34885064, 2021). "However xenograft tumors have been used to reveal PGRMC1′s role in regulating growth parameters, vascular genesis, and response to chemotherapeutics in ovarian and endometrial tumors." (PMID 34885064, 2021).
glucose metabolism disorder (1 paper, 2021). "Potentially, the PGRMC1 target may be regarded as a novel therapeutic strategy for AAPD-induced hepatic glucose metabolism disorder." (PMID 34970218, 2021).
gynecological cancer (1 paper, 2015). "Furthermore, it was shown that overexpression of PGRMC1 interfered with cisplatin-induced cytotoxicity, which suggests that PGRMC1 has a survival role in this particular gynecological cancer." (PMID 25252652, 2015).
hemochromatosis (1 paper, 2023). A disorder of iron metabolism characterized by a triad of HEMOSIDEROSIS; LIVER CIRRHOSIS; and DIABETES MELLITUS. "Now, the question is could the activation of PGRMC1 in the liver be therapeutically relevant for the treatment of hemochromatosis?" (PMID 37834119, 2023). "Consequently, S1R, S2R, PGRMC1, and PGRMC2 potentiate disease progression in hemochromatosis and cancer." (PMID 37834119, 2023).
hyperandrogenism (1 paper, 2016). Excessive secretion of androgens from the adrenal glands or gonads. "The identified differentially expressed biomolecules such as PGRMC1 and 14-3-3ζ might be novel proteins that are closely associated with the pathogenesis of hyperinsulinism and further hyperandrogenism of PCOS." (PMID 27846214, 2016). "PGRMC1 might be linked to the hyperandrogenism mechanism in PCOS." (PMID 27846214, 2016).
Intellectual disability (1 paper, 2021). "A literature search revealed a report of two unrelated males with non-syndromic intellectual disability, as well as congenital cataract, who had contiguous gene deletions that accounted for their intellectual disability but also disrupted the PGRMC1 gene." (PMID 33867527, 2021). "They report two unrelated male patients, with deletions also impacting PGRMC1, who had congenital cataract in addition to intellectual disability." (PMID 33867527, 2021).
iron deficiency (1 paper, 2026). "Although Hmox1 was not upregulated, several heme-scavenging genes (Hpx, Lrp1/Cd91) were induced, while others involved in heme or biliverdin handling (Slc48a1/Hrg1, Pgrmc1, Blvrb) were downregulated, suggesting a compensatory shift in heme-related processes consistent with iron deficiency." (PMID 41598416, 2026).
kidney cancer (1 paper, 2021). Primary or metastatic malignant neoplasm involving the kidney. "High expression of PGRMC1 correlates with poor outcome, which has been reported for breast-, lung-, ovarian- and kidney cancer." (PMID 34830790, 2021).
meningioma (1 paper, 2026). A generally slow growing tumor attached to the dura mater. "Here we show that sex hormone interaction with PGRMC1, a transmembrane progesterone binding protein, regulates the activity of RNA processing proteins FXR1 and RBM39 to drive meningioma sex differences." (PMID 42282014, 2026).
metastatic tumors (1 paper, 2021). "Meanwhile, the expression of FAK was significantly decreased (p < 0.05, 36.9% compared with WT mice) in the metastatic tumors of Pgrmc1 KO mice." (PMID 33832499, 2021).
neuroblastoma (1 paper, 2021). Neuroblastoma (NB) is the most common solid, extracranial childhood tumor. "We demonstrated that downregulation of PGRMC1 is required for IAV replication and propagation in both the human neuroblastoma cell line SK-N-SH and human brain glioma cell line U251." (PMID 34585989, 2021).
ovarian serous cystadenocarcinoma (1 paper, 2024). A malignant serous cystic epithelial neoplasm arising from the ovary. "We also noted better survival rates for patients with ovarian serous cystadenocarcinoma showing high PGRMC1 expression." (PMID 39464509, 2024).
papillary serous cystadenocarcinoma (1 paper, 2015). A malignant cystic serous epithelial neoplasm characterized by the presence of malignant glandular epithelial cells forming papillary structures. "In contrast, PGRMC1 was significantly elevated in serous papillary adenocarcinoma (p = 4 × 10−5), papillary serous cystadenocarcinoma (p = 0.006) and endometroid carcinoma (p = 0.02)." (PMID 27867772, 2015). "PGRMC1 was also elevated in metastatic serous papillary adenocarcinoma compared to normal tissue (p = 0.003), but was not significantly different from the primary serous papillary adenocarcinoma." (PMID 27867772, 2015).
Premature ovarian insufficiency (1 paper, 2022). Amenorrhea due to loss of ovarian function before the age of 40. "Further insight into the capacity of human PGRMC1 to bind progesterone was provided by studies that assessed the capacity of a missense point mutation (H165R) of PGRMC1 which was observed in women with premature ovarian insufficiency." (PMID 35626669, 2022). "Additional support for a role of PGRMC1 in regulating follicle development in women came from the finding that women experiencing premature ovarian insufficiency had lower levels of PGRMC1 in their peripheral leukocytes and/or a functional mutation in PGRMC1." (PMID 35626669, 2022).
retinitis pigmentosa (1 paper, 2017). Retinitis pigmentosa (RP) is an inherited retinal dystrophy leading to progressive loss of the photoreceptors and retinal pigment epithelium and resulting in blindness usually after several decades. "A synthetic form of the female hormone progesterone, Norgestrel, which acts via progesterone receptor membrane component 1, has been proposed as therapeutic for the treatment of retinitis pigmentosa." (PMID 29137141, 2017).
steatosis (1 paper, 2018). Increased lipid within the cytoplasm of cells. "Interestingly, both mRNA (2.09 folds) and protein (1.43 fold) level of Pgrmc1 were increased (P < 0.05) in high-fat-fed WT mice than WT mice fed a normal diet, suggesting that Pgrmc1 can also be used as potential biomarker in steatosis." (PMID 30356113, 2018).
tongue tumors (1 paper, 2015). "For example, the highest levels of staining were located in the tongue, and PGRMC1 was elevated in tongue tumors (n = 16) relative to normal tongue tissue (n = 18, p = 0.009)." (PMID 27867772, 2015).
type II diabetes (1 paper, 2020). "In conclusion, our study suggests that the regulation of gluconeogenesis by PGRMC1 modulation holds great potential as a new therapeutic approach to manage and treat type II diabetes." (PMID 33005004, 2020). "In this study, we demonstrated that P4-mediated PGRMC1 induction increases gluconeogenesis under insulin-resistant conditions such as type II diabetes." (PMID 33005004, 2020).
uterine disease (1 paper, 2013). "In this review we will summarize what is known about PGRMC1/2 in uterine physiology and we will provide examples of disrupted expression of these genes in uterine disease states." (PMID 24065879, 2013). "While the functional importance of PGRMC1/2 in the uterus remains to be fully explored, accumulating evidence suggests that disruption in PGRMC1/2 expression correlates with uterine disease." (PMID 24065879, 2013).
α-synucleinopathies (1 paper, 2023). "S2R in close association with PGRMC1 regulates cell pathways known to be impaired in α-synucleinopathies, such as autophagy, vesicle trafficking, and lipid synthesis." (PMID 37047224, 2023).
cancer (79 papers, 2008 to 2025). A tumor composed of atypical neoplastic, often pleomorphic cells that invade other tissues. "PGRMC1 exhibited a significant correlation with TK1 when all cancers were combined, although the magnitude of these associations was weak (r = 0.154; P = 9 × 10−08)." (PMID 39804138, 2025). "PGRMC1 exhibits a significant correlation with TK1 when all cancers are combined, although the magnitude of these associations is weak." (PMID 39804138, 2025). "While progesterone receptor membrane component 1 (PGRMC1) has been implicated in various cancers, its specific role in cervical carcinogenesis has remained uncertain." (PMID 41153737, 2025). "PGRMC1 overexpression was found in various types of cancer, associated with poor prognosis and aggressiveness, and its overexpression was proposed as a valuable prognosis biomarker." (PMID 38804287, 2024). "These include physiological levels of carbon monoxide, which dissociate the PGRMC1 dimer, cancer-associated mutants in PGRMC1, as well as changes in PGRMC1 phosphorylation or protein-protein interactions." (PMID 37866635, 2023). "Accumulating evidence indicate that PGRMC1 is essential for tumor formation, invasion, and metastasis and is closely associated with an aggressive phenotype and poor prognosis of cancers." (PMID 35152910, 2022). "Several reports have shown that PGRMC1 is highly expressed in various cancer cells, and is associated with tumor progression and chemoresistance." (PMID 34209885, 2021). "PGRMC2, similar to PGRMC1, have been implicated in different cancer signaling cascades, yet with likely tumor suppressor properties." (PMID 34789240, 2021). "PGRMC1 is involved in cell cycle processes at the G1 checkpoint during mitosis, while overexpression of PGRMC1 is associated with adverse prognosis in many types of cancer." (PMID 34513071, 2021). "Progesterone Receptor Membrane Component 1 (PGRMC1) is expressed in many cancer cells, where it is associated with detrimental patient outcomes." (PMID 32245408, 2020). "It is involved in cell cycle processes at the G1 checkpoint and during mitosis, and elevated PGRMC1 expression has been associated with poor prognosis in multiple types of cancer." (PMID 32245408, 2020). "Altogether, these results indicate that mutational manipulation of PGRMC1 phosphorylation status exerts broad pleiotropic effects relevant to cancer and other cell biology." (PMID 32245408, 2020). "Previous studies revealed that PGRMC1 played important roles in cancer proliferation and regulation of the cancer cell susceptibility to chemotherapy." (PMID 31970154, 2019). "PGRMC1 plays a causative role in cancer progression, because in vitro, PGRMC1 increases tumor cell proliferation, chemotherapy resistance and invasion, and in vivo, PGRMC1 increases tumor growth, angiogenesis and metastasis." (PMID 27867772, 2015). "PGRMC1 has been involved in a multitude of other cancer associated signaling pathways." (PMID 34789240, 2021). "Activation of PGRMC1 might be a potential strategy to kill recalcitrant cancer cells via promoting their ferroptosis susceptibility." (PMID 34749765, 2021). "Our present study underlines the potential of PGRMC1 as a target for anti-cancer therapy." (PMID 32660617, 2020). "Moreover, PGRMC1 has been shown to be overexpressed in various cancer types, involved in cancer pathology and has been associated with increased tumor growth in progestin-based hormone therapy." (PMID 29069804, 2017). "PGRMC1 has been previously associated with drug resistance, a characteristic of cancer stem cells." (PMID 27867772, 2015). "PGRMC1 is a membrane-associated protein implicated in the transport of multiple receptors to the plasma membrane, and multiple studies have proposed PGRMC1 ligands as therapeutics or diagnostic agents for cancer." (PMID 27867772, 2015). "Furthermore, PGRMC1 regulates susceptibility of cancer cells to chemotherapy." (PMID 28107520, 2017).